LCN2 (lipocalin 2)
Diseases named in the same sentence as LCN2 in open-access papers (continued):
Sharing a sentence is not in itself a finding about the gene and the disease.
Stroke (continued). "Pathway analysis revealed decreases in genes related to astrocyte function, especially decreases in Lcn2, which has many neuroinflammatory effects in the context of stroke, in the μKO compared to WT." (PMID 37777791, 2023). "When stroke occurs, reactive astrocytes, activated microglia, neurons, choroid plexus and endothelial cells synthesize and secrete LCN2 in response to inflammation or damage to the brain." (PMID 37543589, 2023). "In addition, there is evidence that LCN2 may be linked to worse outcomes post stroke." (PMID 38107410, 2023). "Second, the circulating LCN2 level was measured only once after admission, we therefore unable to evaluate the dynamic changes of LCN2 after stroke." (PMID 36974345, 2023). "Astrocytes promote microglial activation through the production of C-X-C motif chemokine ligand 10 (CXCL10), lipocalin-2 (Lcn2), and complement 3 (C3), as seen in models of stroke and epilepsy." (PMID 37274195, 2023). "LCN2 expression was significantly induced in astrocytes 24 h after stroke onset in the mouse MCAO model." (PMID 37353794, 2023). "Further studies are warranted to determine the pathophysiological role of LCN2 in mediating stroke outcomes." (PMID 36974345, 2023). "Lcn2 is expressed in astrocytes and ECs in the adult mouse brain after middle cerebral artery occlusion in a murine stroke model, while the Lcn2 receptor is expressed in neurons, astrocytes, and endothelial cells." (PMID 38283681, 2023). "Most interestingly, stroke also triggered elevation of proinflammatory Lcn2 mRNA and its protein as well as infiltration of anti-inflammatory myeloid cells in ChP at day 5 post-stroke." (PMID 38107410, 2023). "Lcn-2 was also shown to be elevated in cases of cerebrovascular accidents, such as stroke and myocardial infarction." (PMID 37958332, 2023). "In the animal experimental model, the serum LCN2 concentration of PSD mice was significantly increased and the expression of LCN2 mRNA in the hippocampus was significantly up-regulated at 1–3 weeks after surgery, compared to the stroke control group." (PMID 37543589, 2023). "In summary, we need to further explore the role of LCN-2 in secondary brain injury after stroke and increase the usage of LCN-2 levels in the diagnosis and treatment of stroke." (PMID 35493318, 2022). "Studies have shown that neutralization of LCN-2 is a reasonable therapeutic strategy to alleviate reperfusion injury in stroke." (PMID 35493318, 2022). "Together, these data indicated that NHE1 protein is involved in activation of NF-κB signaling in astrocytes, which in turn regulates LCN2 secretion and LCN2-induced iron accumulation in stroke brains." (PMID 35440572, 2022). "These controversial conclusions can provide new ideas for us to further explore the pathophysiological mechanism of LCN-2 in brain injury after stroke." (PMID 35493318, 2022). "In this study, we investigated the role of astrocytic Na+/H+ exchanger 1 (NHE1) in regulating reactive astrocyte LCN2 secretion and neurodegeneration after stroke." (PMID 35440572, 2022). "Increasing evidence indicated that lipocalin 2 (LCN2), a 25k-Da acute phase protein from the lipocalin superfamily, significantly increased immediately after the stroke and played a vital role in these events." (PMID 36187347, 2022). "Overall, our review suggests that LCN-2 is a promising target to promote a better understanding of the neuropathology of stroke." (PMID 35493318, 2022). "So far, little is known about the signaling pathways that mediate the expression and function of LCN2 in stroke." (PMID 36187347, 2022). "Stroke triggered increase in LCN2 expression (~20 and 25 kDa) in exosomes enriched fraction 2 from the IL hemispheres of wild-type brains." (PMID 35440572, 2022). "Meanwhile, there exists a close relationship between LCN2 levels and the worse clinical outcome of patients with stroke." (PMID 36187347, 2022).
Stroke (continued). "Neutralization of lipocalin-2-attenuated neurological deficits and cerebral infarction by diminishing the expression of M1 macrophage polarization in the brain in a stroke-reperfusion injury mouse model." (PMID 36558562, 2022). "LCN2, a composition of neutrophil secondary granules, is closely related to infiltrated neutrophils after stroke." (PMID 36187347, 2022). "To fully understand the expression landscape of LCN2, we investigated recent research focusing on LCN2 expression and then discussed the possible significant role of LCN2 in the brain after stroke." (PMID 36187347, 2022). "Increasing studies have revealed that LCN2 was an essential mediator of brain injury and a promising therapeutic target following stroke." (PMID 36187347, 2022). "In rodent stroke, LCN2 deficiency reduced infarct volumes, and double-immunofluorescence staining identified GFAP+ astrocytes as the predominant cellular source of LCN2 in the penumbra 24 h after stroke." (PMID 35384588, 2022). "They found that the expression of LCN2 was significantly raised in the stroke and TIA groups than in the control group." (PMID 36187347, 2022). "In summary, these studies suggest that genetic or pharmacological inhibition of these pro-inflammatory mediators (iNOS, IL-6, CCL2, and CCL9) provides neuroprotection against stroke, which can affect pro-inflammatory mediators by modulating LCN-2." (PMID 35493318, 2022). "The lysates of red blood cells are the major factors that induce the expression of LCN2 after stroke." (PMID 36187347, 2022). "Our results further suggest that stroke-induced astrocytic LCN2 upregulation is likely mediated by ER stress-independent mechanisms." (PMID 35440572, 2022). "Here, we review the evidence on the regulatory roles of LCN-2 in secondary injuries following a stroke from various perspectives and the pathological mechanisms involved in the modulation of stroke." (PMID 35493318, 2022). "Astrocyte specific deletion of Nhe1 in Gfap-CreER+/−;Nhe1f/f mice reduced astrogliosis and astrocytic LCN2 and GFAP expression, which was associated with reduced loss of NeuN+ and GRP78+ neurons in stroke brains." (PMID 35440572, 2022). "According to recent research, LCN2 increases rapidly and significantly after stroke and plays a vital role in brain injury." (PMID 36187347, 2022). "LCN2 expression is increased during aging and several neuroinflammatory conditions, including AD, MS and stroke suggesting a role for LCN2 in CNS disorders." (PMID 36034148, 2022). "Bone MSC- (BMSC-) derived exosomes with miR-138-5p target the lipocalin 2 (LCN2) on astrocytes and reduce the neurological impairment by inhibiting the astrocytes' inflammatory response and apoptosis after stroke." (PMID 36052309, 2022). "Especially, LCN2 elevates significantly in plasma and brain of patients and experimental-induced models after stroke." (PMID 36187347, 2022). "Our previous study discovered that LCN2 and its receptor-24p3R were expressed in neurons after stroke." (PMID 36187347, 2022). "LCN2 deficient experimental animals alleviated immune infiltrates, neuronal death, BBB disruption, and neurological deficits under stroke conditions." (PMID 36187347, 2022). "This review focuses on the role of LCN2 and its receptors in brain injury and aiming to find out possible therapeutic targets to reduce brain damage following stroke." (PMID 36187347, 2022). "LCN2 mainly expresses neutrophils, astrocytes, microglia/macrophages, endothelial cells, and neurons in the brain after stroke." (PMID 36187347, 2022). "We also detected decreased ischemia-induced LCN2 secretion in exosomes from astrocytes with NHE1 inhibitor HOE642 or in exosomes from Nhe1 Astro-KO stroke brains, indicating a role of NHE1 protein in the regulation of astrocytic LCN2 expression and secretion." (PMID 35440572, 2022).
Stroke (continued). "In other diseases, use of an anti‐LCN2‐neutralizing antibody showed reductions in reperfusion injury after stroke and attenuated skin lesions in a psoriasis mouse model." (PMID 34342930, 2021). "A recent study has indicated that a LCN2 MAB significantly reduces cerebral infarction and neurological deficits after stroke, suggesting targeting LCN2 as a promising intervention for the therapy of neurological diseases." (PMID 34636748, 2021). "The relative expression of LCN2 was significantly higher in the tumor from stroke mice than that from sham mice, which is consistent with the previous RNA-seq results." (PMID 32153594, 2020). "Treatment with LCN2 mAb at 4 h after tMCAo significantly reduced stroke induced neurological deficits and sensorimotor asymmetry as compared with isotype control antibody treatment." (PMID 32872405, 2020). "Among these genes, we noticed that LCN2 exhibited high expression level and significant upregulation in the stroke mice compared to the sham mice." (PMID 32153594, 2020). "Administration of LCN2 mAb at 4 h after stroke significantly reduced neurological deficits, cerebral infarction, edema, BBB leakage, and infiltration of neutrophils." (PMID 32872405, 2020). "LCN2 mAb administered before the complete rise of LCN2 after stroke not only attenuated the levels of LCN2 itself, but also reduced the induction of pro-inflammatory chemokines and cytokines." (PMID 32872405, 2020). "Instead, the percentage of LCN2+ cells among CD45+ cells and the number of LCN2+CD45+ cells were significantly increased in the tumor after stroke, suggesting that the increased LCN2 were mainly derived from leukocytes." (PMID 32153594, 2020). "Genetic deletion of LCN2 significantly reduces brain injury after stroke, suggesting that LCN2 is a mediator of reperfusion injury and a potential therapeutic target." (PMID 32872405, 2020). "LCN2 mAb specifically immunoprecipitated recombinant LCN2 protein, as well as endogenous LCN2 protein induced in blood sera and ischemic brain tissues after stroke." (PMID 32872405, 2020). "The percentage of LCN2+ cells among PMN-MDSCs were also decreased in the stroke mice compared to the sham mice." (PMID 32153594, 2020). "The pro-inflammatory mediators regulated by LCN2 have been demonstrated to play key roles in stroke-reperfusion injury." (PMID 32872405, 2020). "Plasma levels of LCN2 are significantly elevated in ischemic stroke patients with unfavorable modified Rankin scale scores, post-stroke infections, hemorrhagic transformations after tPA treatments, and cardiovascular mortality." (PMID 32872405, 2020). "We observed an acute induction of LCN2 protein after stroke in infiltrating neutrophils, cerebral endothelial cells, and astrocytes gatekeeping the BBB." (PMID 32872405, 2020). "We found that compared to the sham mice, the stroke mice had significantly fewer LCN2+ CD45+CD11b+Ly6GhiLy6Clow cells and LCN2+ CD45+CD11b+Ly6GlowLy6Chi cells in the peripheral blood." (PMID 32153594, 2020). "We found that there are significantly more LCN2+ Gr1+ cells in the tumor of stroke mice than that in the sham mice." (PMID 32153594, 2020). "We believe that this study is the first to validate the concept that neutralization of LCN2 is a plausible therapeutic strategy to reduce stroke-reperfusion injury." (PMID 32872405, 2020). "To explore the underlying mechanism, we performed RNA-sequencing analysis of the tumor tissue from mice with or without stroke and found prominent upregulation of lipocalin 2 (LCN2) in the tumor from stroke mice compared to those from sham mice." (PMID 32153594, 2020). "Under inflammatory conditions, astrocytes secrete Lipocalin-2 (LCN2)—a molecule that has recently been discussed as a valuable biomarker for the prediction of clinical outcome in stroke patients." (PMID 30871254, 2019).
Stroke (continued). "In a next step, we performed immunohistochemistry and double-immunofluorescence staining against LCN2 to pinpoint more precisely the cellular source of LCN2 in the peri-infarct area 24 h after stroke onset." (PMID 30871254, 2019). "After focal cerebral ischemia in rats, plasma levels of LCN2 were significantly elevated at 6, 12, and 24 hrs, and persisted until 3 days post-stroke." (PMID 31269059, 2019). "In human stroke, serum levels of LCN2 progressively increased following acute ischemia and transient ischemic attacks." (PMID 31269059, 2019). "RT-qPCR analysis of Lcn2 confirmed significant upregulation at 2–5 days after experimental stroke in comparison to sham." (PMID 29872438, 2018). "Microarray analysis showed increased expression of transcripts for Cd163 and Lcn2 (Lipocalin2) 1–5 days after experimental stroke in comparison to sham-operated controls." (PMID 29872438, 2018). "The presence of LCN2 in rat tMCAO and postmortem human ischemic brain was previously reported up to 3 days post stroke." (PMID 27152948, 2016). "In contrast to patients with mRS 0–2, those who had mRS 3–6 showed significantly higher median plasma levels of LCN2 measured one week after stroke (75.5 vs. 43.4 ng/ml; p = 0.03)." (PMID 27152948, 2016). "The strength of our study is the exact timing with a predefined interval from stroke onset to blood sampling to include information about changes of circulating LCN2 upon ongoing post-stroke infections." (PMID 27152948, 2016). "Our study shows that LCN2, measured in peripheral blood one week after stroke onset, is an infection-related biomarker related to the clinical outcome at 90 days." (PMID 27152948, 2016). "Previous studies revealed a role of LCN2 in the migration of astrocytes, microglia and neurons by the induction of chemokine expression, thereby suggesting favorable effects of LCN2 in post-stroke remodeling." (PMID 27152948, 2016). "It suggests that Lcn2 is a potential early stroke biomarker and a novel therapeutic target to reduce injury." (PMID 27213359, 2016). "A correlation of LCN2 plasma levels with the mRS at 90 days after stroke was found (rS = 0.40; p<0.01)." (PMID 27152948, 2016). "In ischemic stroke patients, higher plasma levels of LCN2 measured one week after stroke correlated with worse clinical outcome at 90 days in our study." (PMID 27152948, 2016). "Since peripheral blood neutrophils are activated during the first few hours after stroke, the elevated LCN2 in plasma is likely derived from activated neutrophils." (PMID 25890235, 2015). "During a 4-year follow-up, stroke patients with higher levels of LCN2 had higher cardiovascular mortality." (PMID 25702801, 2015). "Our results demonstrate that LCN2 is a neurotoxic factor secreted rapidly in response to cerebral ischaemia, suggesting its potential usage as an early stroke biomarker and a novel therapeutic target to reduce stroke-reperfusion injury." (PMID 25702801, 2015). "To assess the effect of stroke-induced LCN2 in vivo, we subjected WT and Lcn2−/− mice to tMCAO with 1 hr of ischaemia followed by 23 hrs of reperfusion." (PMID 25702801, 2015). "Expression of LCN2 after stroke was increased not only in sera but also in brain, where it was localized to infiltrating neutrophils and a subset of astrocytes." (PMID 25702801, 2015). "Here, we report that LCN2 increases rapidly in response to cerebral ischaemia and promotes reperfusion injury in murine stroke." (PMID 25702801, 2015). "LCN2 has been identified as an important mediator of stroke-reperfusion injury and white matter injury after ischemic and hemorrhagic strokes." (PMID 30542675, 2015). "We detected the induction of LCN2 in mouse serum within 1 hr after tMCAO, suggesting the possibility of using LCN2 as an early blood biomarker of stroke." (PMID 25702801, 2015). "This review is an attempt to summarize some LCN2-related research findings and discuss its role in stroke." (PMID 30542675, 2015).
Stroke (continued). "We recently found that brain injury, neurological deficits, and infiltration of immune cells were markedly diminished in LCN2 null mice when compared with wild type mice after stroke-reperfusion injury." (PMID 25890235, 2015). "Immunofluorescence analysis 24 h after stroke corroborated Msr1 and LCN2 expression." (PMID 38988493, 2024). "In addition, we analyzed the differences in the expression of serum LCN2 levels between stroke subtypes, and patients in the large artery atherosclerosis group had significantly higher serum LCN2 levels than those in the small-artery occlusion group." (PMID 37543589, 2023). "In our study, higher LCN2 mRNA level than LCN2 protein was detected in LVCPs in post-stroke brains." (PMID 38107410, 2023). "In addition, for some diseases, such as stroke–reperfusion injury, monoclonal anti-Lcn-2 antibodies are used as a potential therapeutic modality." (PMID 37958332, 2023). "Recent research suggests stroke-triggered reactive astrocytes overexpress lipocalin 2 (LCN2), binding to low-density lipoprotein receptor-related protein 1 (LRP1), activating phagocytosis and inducing astrocytes to phagocytose myelin fragments, causing demyelinating lesions." (PMID 37720543, 2023). "The LCN2-decreasing CFH variants reported here were found by MR to causally reduce blood pressure, body mass index and waist-to-hip ratio, but increase risk of stroke, triglycerides and LDL levels." (PMID 37778719, 2023). "Similarly, Lcn2 is involved in ischemic stroke reperfusion injury and increases in brain Lcn2 levels after stroke play a role in mediating subsequent brain injury by activating astrocytes." (PMID 38283681, 2023). "However, the IL LVCP displayed significant increase of LCN2 at day 1, which gradually decreased during days 5 and 7 post-stroke (P < 0.05)." (PMID 38107410, 2023). "In this regard, LCN2 has been shown to contribute to the inflammatory reaction by increasing the expression of inflammatory cytokines and exacerbating the pathological process in some disease models, including stroke and nonalcoholic steatohepatitis." (PMID 37240031, 2023). "Upregulated levels of LCN2 in plasma and CSF predict an unfavorable prognosis in stroke patients." (PMID 36187347, 2022). "Increasing evidence emphasizes the role of LCN2 in these signs of progress after stroke." (PMID 36187347, 2022). "High expression of LCN2 was associated with brain edema, BBB leakage, immune cell infiltration, glial cell activation and polarization, neuronal death, hydrocephalus, and neurological deficits in stroke models." (PMID 36187347, 2022). "Blocking astrocytic NHE1 activity is beneficial to reduce LCN2-mediated neurotoxicity after stroke." (PMID 35440572, 2022). "Administration of LCN-2 mAb prior to full post-stroke LCN-2 elevation reduced the levels of LCN-2 and pro-inflammatory mediators (iNOS, IL-6, CCL2, and CCL9) and resulted in neutrophil infiltration, BBB leakage, cerebral infarction induction, and improved functional outcomes after stroke." (PMID 35493318, 2022). "LCN2 not only plays a role in damage in stroke but also has a partial protective effect." (PMID 36187347, 2022). "Expression of LCN2 in the plasma and brain of stroke patients and stroke-induced animal models." (PMID 36187347, 2022). "Since NHE1-mediated H+ extrusion promotes NOX-2 activation in neurons and glial cells to prevent acidic pHi-induced NOX inhibition, we sought to determine whether increased NOX activity contributed to augmented LCN2 expression in RA after stroke." (PMID 35440572, 2022). "LCN2 may exert neuroprotective effects by affecting the expression of inflammatory cells and inflammatory factors after stroke." (PMID 36187347, 2022). "Hypoxic conditions, thrombin, PRDX2, and iron contribute to the increase of LCN2 after stroke." (PMID 36187347, 2022).